FAM72D (family with sequence similarity 72 member D)
Synonyms: GCUD2
Tractability: Antibody: the Human Protein Atlas places it where antibodies can reach. PROTAC: ubiquitination databases record sites on it.
Gene: Protein-coding gene on chromosome 1 (145,095,971 to 145,112,696, forward strand). Ensembl gene ENSG00000215784.
Subcellular location (Human Protein Atlas): Vesicles; Cytosol; Plasma membrane
Gene Ontology:
Molecular function: protein binding
Cellular component: cytosol
Genetic constraint (gnomAD): Loss-of-function variants: 0 observed, 0.46 expected, observed/expected ratio (o/e) 0, 90% interval 0 to 1.84. That is too few expected variants to judge how well the gene tolerates losing a copy. Missense variants: 0 observed, 15.71 expected, observed/expected ratio (o/e) 0, 90% interval 0 to 0.19. Synonymous variants: 0 observed, 3.83 expected, observed/expected ratio (o/e) 0, 90% interval 0 to 0.78.
Homologues: Orthologues: chimpanzee FAM72A (99% identical), macaque FAM72A (99% identical), guinea pig Fam72a (92% identical), mouse Fam72a (89% identical), rat Fam72a (89% identical), dog FAM72A (78% identical), zebrafish FAM72A (62% identical), tropical clawed frog fam72a (52% identical). Paralogues in human: FAM72C (99% identical), FAM72A (99% identical), FAM72B (97% identical).
Diseases named in the same sentence as FAM72D in open-access papers:
FAM72D is named in the same sentence as 9 diseases in open-access papers, as found by Europe PMC text mining. Sharing a sentence is not in itself a finding about the gene and the disease. The quoted sentences say what the papers report.
multiple myeloma (2 papers, 2020 to 2025). "In multiple myeloma, the DNA demethylation of the FAM72D gene is closely associated with enhanced tumor cell proliferation and can serve as a prognostic biomarker for this malignancy." (PMID 41153357, 2025). "FAM72D, located in the 1q21.1 region of the human chromosome, has demonstrated significant potential as a prognostic biomarker in multiple myeloma, prostate cancer, kidney renal clear cell carcinoma (KIRC), HCC, and LUAD." (PMID 41153357, 2025). "The family with sequence similarity 72 member D (FAM72D) is also known as GCUD2; it is a poor prognostic gene of myeloma and control cell proliferation and survival in the FOXM1 transcription factor network." (PMID 32566639, 2020).
glioblastoma multiform (1 paper, 2019). "FAM72D, a family with sequence similarity 72 member D, can be considered to be a target gene in glioblastoma multiform (GBM)." (PMID 31739630, 2019).
prostate carcinoma (1 paper, 2020). A carcinoma that arises from epithelial cells of the prostate gland. "FAM72D, ARHGAP33, TACR2, PLEK2, and FA2H were identified as independent prognosis factors in prostate cancer patients." (PMID 32566639, 2020).
cancer (5 papers, 2017 to 2021). A tumor composed of atypical neoplastic, often pleomorphic cells that invade other tissues. "FAM72D was reported to be a new target for cancer therapies since its expression correlates with UBE2C, whose higher expression leads to a worse OS prognosis." (PMID 31739630, 2019).
tumor (2 papers, 2019 to 2024). "In particular, our data highlighted MTFR2, MND1, FAM72D, and POC1A as genes whose expression correlates with worse OS prognosis, suggesting their possible involvement in tumor progression and invasion." (PMID 31067633, 2019).
FAM72D also shares sentences with these, for which no sentence is quoted: breast carcinoma (2 papers); hepatic cancer (1); hepatocellular carcinoma (1); ovarian carcinoma (1).